NLRP3 (NLR family pyrin domain containing 3)
Diseases named in the same sentence as NLRP3 in open-access papers (continued):
Sharing a sentence is not in itself a finding about the gene and the disease.
varicocele (12 papers, 2020 to 2025). A condition characterized by the dilated tortuous veins of the spermatic cord with a marked left-sided predominance. "Western blot analysis revealed that apoptosis associated speck-like protein (ASC, P=0.0002)and NLRP3 (P=0.005) were significantly elevated in the semen of varicocele patients." (PMID 32112635, 2020). "The mRNA levels of NLRP3, apoptosis-associated speck-like protein containing a caspase recruitment domain, and caspase-1 were evaluated by real-time polymerase chain reaction at 1, 2, 4, 8, and 12 wk after varicocele induction." (PMID 37727396, 2023). "ROS activates the NLRP3 inflammasome to trigger pyroptosis (e.g., mtROS accumulation in varicocele), while inducing autophagy to clear the damaged component." (PMID 40331931, 2025). "Chlorogenic acid inhibits cGAS/STING-mediated NLRP3 activation in varicocele, restoring mitochondrial homeostasis." (PMID 40331931, 2025). "Virtual screening identified FDA-approved drugs (ChEMBL IDs: 4297185, 1201749, 1200545) targeting NLRP3 for varicocele treatment." (PMID 40331931, 2025). "Their study found that serum and seminal plasma NLRP-3 and IL-1β levels in patients with varicocele or azoospermia were significantly higher than in those without either condition." (PMID 39712014, 2024). "This showed us that besides varicocele, azoospermia significantly increases NLRP3 levels; thus, this proinflammatory molecule gains more importance in azoospermic and patients with varicocele." (PMID 37476898, 2023). "We aim to determine the time course of NLRP3 inflammasome expression in the testis tissue following varicocele induction." (PMID 37727396, 2023). "Our data provides clear evidence that varicocele stimulates inflammasome activation in the testis tissue 12 wk after the operation, and this time is required for investigating NLRP3 activity in the varicocele rat model." (PMID 37727396, 2023). "Our results determined that 12 wk after varicocele induction is the best time for evaluating the role of the NLRP3 inflammasome in the pathogenesis of varicocele." (PMID 37727396, 2023). "As the western blot was not performed, the best time for evaluating the effects of the NLRP3 inflammasome on rat male fertility is 12 wk after varicocele induction." (PMID 37727396, 2023). "Given that inhibiting the inflammasome complex reduces the destructive effects of varicocele on testis tissue, controlling the expression of the NLRP3 inflammasome as adjuvant therapy appears to be a promising target for alleviating varicocele complications." (PMID 37727396, 2023). "It seems that a group of cytosolic receptors named nod-like receptor family, pyrin domain containing 3 (NLRP3) inflammasome, is activated and involved in the pathogenesis of varicocele." (PMID 37727396, 2023). "Finding this time course of inflammasome activity is important for clarifying the mechanism related to the NLRP3 complex in varicocele for further studies." (PMID 37727396, 2023). "In our previous work, we detected NLRP3, apoptosis-associated speck-like protein containing a caspase recruitment domain (ASC), and IL-1b in the semen of varicocele patients." (PMID 37727396, 2023). "The roles of selenium and Polydeoxyribonucleotide (PDRN) were investigated in an experimental model of varicocele, with particular regard to the role of NLRP3 inflammasome." (PMID 33525681, 2021). "One of the main inflammatory pathways induced by varicocele is the NLRP3 inflammasome pathway, as recently demonstrated in animal models and in humans." (PMID 33668991, 2021). "Overall, our results suggest that, in line with our previous study, PEA-um, via a TLR4-dependent pathway, selectively restores the expression of claudin-11 and occludin and reduces the expression of TGF-β3, p-ERK 1/2 and NLRP3 in varicocele mice." (PMID 33668991, 2021).
varicocele (continued). "Recently, in an experimental model of varicocele, an upregulation of the levels of NLRP3 inflammasome was demonstrated, which was decreased by the administration of resveratrol, a nutraceutical compound provided of anti-inflammatory properties." (PMID 33525681, 2021). "The treatment with Se or PDRN significantly reduced NLRP3 mRNA expression in both operated and contralateral testes when compared to the testes of varicocele rats (p < 0.0001 versus varicocele rats)." (PMID 33525681, 2021). "In varicocele animals, lower testosterone levels, testes weight, NLRP3 inflammasome, IL-1β and caspase-1 increased gene expression were demonstrated." (PMID 33525681, 2021). "Therefore, this study suggests that NLRP3 inflammasome can be considered an interesting target for innovative bioactive compounds aimed to treat testicular injury after varicocele and that the association Se and PDRN may be used as a new medical approach in support to surgery for varicocele." (PMID 33525681, 2021). "The aim of this study was toinvestigate expression of nod-like receptor family, pyrin domain containing 3 (NLRP3) inflammasome componentsand cytokines in semen of varicocele and control subjects." (PMID 32112635, 2020). "NLRP3 (P=0.005) andASC (P=0.0002) protein levels were significantlyelevated in varicocele patients versus control subjects(relative intensity of ASC was 2.02 ± 0.09 vs. 0.32 ± 0.28and relative intensity of NLRP3 was 1.5 ± 0.13 vs. 0.56 ±0.1, respectively)." (PMID 32112635, 2020). "This study provides the first evidence of activation of NLRP3 components in semen of men with varicocele." (PMID 32112635, 2020). "In our previuos work, we showed high levels ofASC, NLRP3 and caspase 1 expression in the testis tissueof varicocele-induced rats, three months after surgery." (PMID 32112635, 2020). "The serum level of IL-1β was also significantly reduced in ZYP-treated rats, suggesting that ZYP may act as an NLRP3 inhibitor, suppressing the IL-1β-dependent inflammatory response in the testicles of varicocele-affected rats." (PMID 40429786, 2025). "Furthermore, the experimental varicocele model study of ZYP is so similar to and supports the previous study that showed the involvement in the activation of potential inflammatory pathways, such as the NLRP3 pathway in varicocele-induced infertility." (PMID 40429786, 2025). "It was suggested that NLRP3 might be a new idea and target for treating varicocele and testicular transplantation." (PMID 39840312, 2024). "The findings of this study indicate that NLRP3 activation occurs in varicocele and may be responsible for the pathological process that occurs in varicocele patients." (PMID 37476898, 2023). "Although we could not detect any significant changes in the level of expression of the NLRP3 inflammasome before the 12th wk, changes were reported in NLRP3, caspase-1, and IL-1b mRNA levels 2 months after varicocele induction." (PMID 37727396, 2023). "As a result, they thought that NLRP3 inflammasome could be considered an interesting target in varicocele and that Se-PDRN could be a new medical approach supporting surgery." (PMID 37476898, 2023). "Furthermore, varicocele induction led to an increase in NLRP3 expression in WT and KO animals, with a marked reduction in TLR4 KO mice." (PMID 33668991, 2021). "Our results suggest that NLRP3 inflammasome can be considered an interesting target in varicocele and that Se-PDRN may be a new medical approach in support to surgery." (PMID 33525681, 2021). "Furthermore, the presence of the NLRP3 inflammasome components in the semen of varicocele patients was also shown." (PMID 33525681, 2021). "Therefore, the aim of this study wasto investigate presence of NLRP3 complex in seminalplasma of varicocele patients." (PMID 32112635, 2020).
varicocele (continued). "The details of the NLRP3 inflammatory activation process have not yet been clarified, and whether NLRP3 is caused by the onset of varicocele or is a pathological consequence of this gonadal disease course." (PMID 37476898, 2023). "Given that in our study, 12 wk after varicocele induction, we could detect changes in the NLRP3 inflammasome expression level, this long time for altering the level of expression of the inflammasome complex might be related to the pathogenesis of varicocele." (PMID 37727396, 2023). "Therefore, it seems that overexpression of NLRP3 might be one of the reasons involved in infertility following varicocele." (PMID 37727396, 2023). "Furthermore, some antioxidants or anti-inflammatory agents, such as resveratrol, selenium, and polydeoxyribonucleotide, have been shown to reduce varicocele complications by downregulating the NLRP3 inflammasome, reducing apoptosis, and increasing testosterone levels." (PMID 37727396, 2023). "The association of Se plus PDRN markedly reverted the increase in the message of NLRP3, demonstrating a greater effect than that of the two compounds alone (p < 0.0001 versus varicocele rats; p < 0.0001 versus varicocele + Se; p < 0.0001 versus varicocele + PDRN)." (PMID 33525681, 2021). "Autophagy inhibits pyroptosis hyperactivation by degrading the NLRP3 inflammasome, e.g., chlorogenic acid inhibits NLRP3 through the cGAS/STING pathway and ameliorates varicocele." (PMID 40331931, 2025). "We analyzed the mRNA expression of NLRP3, ASC, and caspase-1, the key inflammatory markers, during 1, 2, 4, 8, and 12 wk after varicocele induction in both left and right testes." (PMID 37727396, 2023). "A significant increase in NLRP3 expression was detected in vehicle WT, PPAR-α KO, and TLR4 KO varicocele mice, compared to the sham operated animals of the same groups." (PMID 33668991, 2021). "In WT and TLR4 KO varicocele animals administered with PEA-um, a substantial reduction of NLRP3 expression was demonstrated." (PMID 33668991, 2021). "In this study, we analyzed relationship of spermparameters with NLRP3, ASC, IL-18 and caspase-1 inboth control and varicocele groups." (PMID 32112635, 2020). "During the 1, 2, 4, and 8 wk after varicocele induction, no significant changes were observed (p = 0.09) in the level of expression of NLRP3, ASC, and caspase-1 in both testes compared to the control group." (PMID 37727396, 2023). "In our study, NLRP3 serum and semen values were varicocele compared to patients without azoospermia and varicocele." (PMID 37476898, 2023). "In our study, the NLRP3 value was higher in azoospermic and varicocele patients (Group 4) compared to groups without varicocele (Group 1–3) and was not significantly higher than those with varicocele but without azoospermia (Group 2)." (PMID 37476898, 2023). "Findings obtained from this study suggest that NLRP3activation occurs in varicocele and it might be responsiblefor pathological procedure occurring in varicocele patients.Details of the NLRP3 inflammasome activation processhas not been clarified yet." (PMID 32112635, 2020). "Serum and semen NLRP3, IL1β, TAS, TOS, and OSI values of the patients with varicocele or azoospermia were significantly higher than those without either varicocele or azoospermia (p < 0.05)." (PMID 37476898, 2023). "In our study, like NLRP3, IL1-semen and serum values were studied in all groups, and serum values were significantly higher in patients with varicocele alone (Group 2–4) compared to patients without azoospermia and varicocele (Group 1) regardless of the azoospermia status." (PMID 37476898, 2023).
vitiligo (12 papers, 2008 to 2024). Generalized well circumscribed patches of leukoderma that are generally distributed over symmetric body locations and is due to autoimmune destruction of melanocytes. "Also, NALP1, a homolog of NLRP3, has recently been shown to be associated with vitiligo-associated multiple autoimmune disease." (PMID 18576390, 2008). "In addition, polymorphisms in NALP1, a gene related to the HPFS gene NLRP3, were recently shown to confer susceptibility to vitiligo-associated autoimmune disease." (PMID 18576390, 2008). "NLRP3 expression has been elevated in perilesional vitiligo skin, which correlates with increased cutaneous IL-1β expression and disease severity." (PMID 36920542, 2023). "Oxidative stress-induced keratinocyte derived NLRP3 activation promotes cutaneous T cell response and can be targeted to treat vitiligo." (PMID 37737154, 2023). "Oxidative stress promotes the expression of NLRP3 and downstream cytokine IL-1β in keratinocytes of patients with vitiligo." (PMID 34768860, 2021). "Both nucleotide-binding oligomerization domain, leucine rich repeat and pyrin domain containing 1 (NLRP1) and the NLRP3 inflammasome have been reported to act in the pathogenesis of vitiligo." (PMID 34768860, 2021). "Oxidative stress–induced NLRP3 inflammasome activation in keratinocytes promotes cutaneous T-cell responses in vitiligo." (PMID 32528469, 2020). "Although the drugs targeting IL-1β have been used in some NLRP3-related diseases, the concerns regarding this treatment in vitiligo existed." (PMID 32754591, 2020). "In addition, our previous study illustrated that the expression of NLRP3 and downstream cytokine of IL-1β is upregulated in peripheral keratinocytes of vitiligo." (PMID 32754591, 2020). "This indicates that the NLRP3 inflammasome and its downstream cytokines may be promising therapeutic targets for vitiligo treatment." (PMID 32528469, 2020). "Thus, we hypothesize that increased CIRP might stimulate the activation of NLRP3 inflammasome that subsequently induce IL-1β involved in vitiligo pathogenesis." (PMID 36920542, 2023). "Regarding the NLRP3 inflammasome, both protein and mRNA concentrations of NLRP3 and IL-1β were found increased in perilesional epidermal samples of vitiligo patients with progressive disease compared to healthy controls and vitiligo patients with stable disease." (PMID 37325658, 2023). "Thus, the directly inhibiting NLRP3 inflammasome might be a better choice than targeting IL-1β for vitiligo treatment." (PMID 32754591, 2020). "Hence, targeting the NLRP3-IL-1β pathway may be another complementary and promising way in vitiligo treatment." (PMID 32754591, 2020). "In the skin during progressive vitiligo, IL-1β is increased with activation of NOD-like receptor family pyrin domain containing 3 (NLRP3) inflammasomes." (PMID 34638746, 2021). "Some NLRs, such as NLRP1 and NLRP3, are activated in response to oxidative stress or cellular damage in vitiligo; NLRP1 and NLRP3 are components of the inflammasome complex that, once activated, releases caspase 1 and IL-1β and IL-18." (PMID 34768860, 2021). "The High-mobility group protein B1 (HMGB1), as a pro-inflammation factor in the downstream of NLRP3 inflammasome, has been proved to facilitate the secretion of IL-8 and CXCL16 in keratinocytes which contributed remarkably to the pathogenesis of vitiligo." (PMID 32754591, 2020). "Deactivation of the NLRP3 inflammasome impaired CD8+ T cell recruitment and inhibited cytokine secretion in T cells derived from vitiligo patients." (PMID 32528469, 2020). "In addition, inactivation of the NLRP3 inflammasome in keratinocytes impaired CD8+ T cell recruitment and inhibited cutaneous T-cell response in patients with vitiligo." (PMID 33534121, 2021).
age (11 papers, 2016 to 2025). A temporal measurement of the time period elapsed since an identifiable point in the life cycle of an organism. "As PWH live longer on ART and face a greater risk of age-related neuroinflammatory conditions, these findings point to the need for novel therapeutic strategies targeting NLRP3 to manage neuropathogenesis associated with cognitive dysfunction." (PMID 41280902, 2025). "The NLRP3-inflammasome is important for the initiation and processing of neuroinflammatory processes, and especially in AD, NLRP3 is associated with age-related inflammation." (PMID 30261895, 2018). "Since the molecular underpinnings of senescence, NF-kB-linked NLRP3 assembly, is modifiable, age-related neurodegenerative disorders could be epigenetically, pharmacologically, and immunometabolically influenced not only from within the CNS but also from the body periphery." (PMID 31297054, 2019). "Elevated levels of pro-inflammatory cytokines secondary to NLRP-3 inflammasome activation, such as IL-1β, are often detected in elderly individuals correlating with age-related CVD." (PMID 32604981, 2020). "Dysfunctional mitochondria contribute to increased cellular stress and an innate immune response by activating the NLRP-3 inflammasomes, which have a role in inflammaging and age-related CVD pathogenesis." (PMID 32604981, 2020). "Age- and tau-related neuroinflammation is characterized by immune activation, glial cell (microglia and astrocytes) reactivity, and the release of neurotoxic, pro-inflammatory cytokines, and many of these events involve signaling via NF-κB and NLRP3." (PMID 39068433, 2024). "Moreover, the most abundant ketone body, β-hydroxybutyrate, inhibits the NLRP3 inflammasome in myeloid cells, a key potentiator of age-related inflammation." (PMID 36775129, 2023). "In conclusion, our study clarifies the early morphological markers of cardiac aging and also supports the role of the NLRP3 inflammasome in the development of age-dependent cardiac sarcopenia, in addition to the protective effect of melatonin supplementation in prevention of cardiac aging." (PMID 34439517, 2021).
alcoholic liver diseases (11 papers, 2017 to 2024). A disorder caused by damage to the liver parenchyma due to alcohol consumption. "Previous research has proven that activation of NLRP3 in hepatic macrophages and molecular chaperone heat shock protein 90 (HSP90) is associated with the induction of Alcoholic liver disease." (PMID 38612538, 2024). "Purinergic signaling (notably through P2X7 receptors and the NLRP3 inflammasome) by Kupffer cells appears to be a decisive factor in the pathophysiology of alcoholic liver disease." (PMID 33670021, 2021). "Choudhury and others reported that HSP90 promoted activation of NLRP3 inflammatory bodies during infection and inflammatory diseases and induced and regulated pro-inflammatory cytokines, tumor necrosis factor α, and IL-6 in Alcoholic liver disease." (PMID 38612538, 2024). "In models related to inflammation such as alcoholic liver disease and high-fat diet, previous studies demonstrated that anthocyanins could inhibit NLRP3 inflammasome activation, but the role of mitophagy of immune cells was not discussed." (PMID 34768852, 2021). "Above results showed that magnolol could prevent alcoholic liver damage, and the underlying mechanism was through activating PI3K/Nrf2/PPARγ signaling pathways as well as inhibiting NLRP3 inflammasome, which also suggested magnolol might be used as a potential drug for ALD." (PMID 31920652, 2019).